ULK4 (unc-51 like kinase 4)
Description:
Pseudokinase that acts as a molecular adapter in the smoothened signaling pathway. Required to relieve inhibition of the GLI2 transcription factor in the presence of hedgehog (DHH, IHH or SHH) ligand: acts by mediating the association between STK36 and its ligand GLI2 in ciliary tip, promoting GLI2 phosphorylation and dissociation from SUFU inhibitor, followed by GLI2 translocation to the nucleus.
Synonyms: FLJ20574; REC01035; FAM7C1
Tractability: Small molecule: a structure with a bound ligand is known; it belongs to a druggable protein family.
Gene: Protein-coding gene on chromosome 3 (41,246,599 to 41,962,130, reverse strand). Ensembl gene ENSG00000168038.
Subcellular location: Cell projection, cilium
Subcellular location (Human Protein Atlas): Cytosol; Primary cilium transition zone
Gene Ontology:
Molecular function: ATP binding; protein binding; protein serine/threonine kinase activity; protein-macromolecule adaptor activity; protein kinase activity
Biological process: microtubule cytoskeleton organization; positive regulation of smoothened signaling pathway; protein kinase C deactivation; regulation of JNK cascade; regulation of MAPK cascade; regulation of neuron migration; regulation of neuron projection development; regulation of p38MAPK cascade; regulation of signal transduction
Cellular component: ciliary tip; cilium
Genetic constraint (gnomAD): Loss-of-function variants: 103 observed, 128.63 expected, observed/expected ratio (o/e) 0.8, 90% interval 0.68 to 0.94. The upper end of that interval is the gene's LOEUF score, 0.94, which puts it in group 4 of 6, group 1 being the genes least tolerant of losing a copy. Missense variants: 1,404 observed, 1,385.6 expected, observed/expected ratio (o/e) 1.01, 90% interval 0.97 to 1.06. Synonymous variants: 474 observed, 507.9 expected, observed/expected ratio (o/e) 0.93, 90% interval 0.87 to 1.01.
Homologues: Orthologues: chimpanzee ULK4 (99% identical), macaque ULK4 (93% identical), dog ULK4 (89% identical), pig ULK4 (88% identical), mouse Ulk4 (83% identical), rat Ulk4 (83% identical), rabbit ULK4 (78% identical), tropical clawed frog ulk4 (61% identical), zebrafish ulk4 (55% identical). Paralogues in human: STK36 (20% identical).
Diseases named in the same sentence as ULK4 in open-access papers:
ULK4 is named in the same sentence as 57 diseases in open-access papers, as found by Europe PMC text mining. Sharing a sentence is not in itself a finding about the gene and the disease. The quoted sentences say what the papers report.
Hypertension (13 papers, 2012 to 2025). The presence of chronic increased pressure in the systemic arterial system. "Ulk4 has been implicated in several human diseases, including hypertension and psychiatric disorder such as schizophrenia." (PMID 38096226, 2023). "ULK4 is a significant genetic risk factor for systemic hypertension and was upregulated with obesity in lung art, heart art, kidney art, brain art and gECs." (PMID 36400935, 2022). "Several reports have mentioned the association between the ULK4 gene and heart disorders, including acute aortic dissections and hypertension." (PMID 35629146, 2022). "Several GWASs have reported significant associations of ULK4 SNPs with hypertension in individuals of European (particularly those with high diastolic blood pressure), African American, and East Asian descent." (PMID 36118886, 2022). "Ulk4 was the only high-risk hypertension gene that was systemically upregulated in art ECs with obesity." (PMID 36400935, 2022). "Based on the results, we can see that the haplotype containing SNP rs2700464 on ULK4 is strongly associated with our defined hypertension outcome." (PMID 25519392, 2014). "One haplotype from a candidate block of gene ULK4 had significant association with hypertension in the main effect model." (PMID 25519392, 2014). "The protein-coding gene ULK4, located near rs7647561, is associated with blood pressure regulation and hypertension, though its exact regulatory mechanism remains unknown." (PMID 40166017, 2025). "Similarly, variants of Unc-51-like kinase 4 (ULK4), a pseudokinase thought to remodel the cytoskeleton, have been linked to aortic dissections, with variants in ULK4 having also been linked to hypertension." (PMID 36561772, 2022). "Multiple GWAS studies have identified a significant association of the ULK4 SNPs with hypertension." (PMID 36118886, 2022). "Genes of ULK4 and FHIT have the highest number of hypertension-associated SNPs for genes mentioned in previous studies (Supplementary S5)." (PMID 35629146, 2022). "Findings from previous GWAS indicated ULK4 and MAP4 genes, encoding, respectively, a Serine/Threonine-Protein Kinase and a non-neuronal microtubule-associated protein, as related to BP and hypertension." (PMID 29495593, 2018). "Several variants have been implicated earlier on ULK4 and MAP4 genes on chromosome 3 to be associated with hypertension." (PMID 27980663, 2016). "We found 1 block from the ULK4 gene and 2 blocks from the LOC64690 gene that were significantly associated with hypertension." (PMID 25519392, 2014). "Among these SNPs, several are relevant to disorders common in Qataris, including type 2 diabetes (UTS2), breast cancer (AKAP13), hypertension (ULK4), and nicotine dependence (FMO2)." (PMID 23139751, 2012). "ULK4 and CYP2D have been reported to be associated with blood pressure and hypertension." (PMID 39734234, 2024). "The ULK4 gene is located at chromosome 3p22.1 and encodes for a member of the unc-51-like serine/threonine kinase (STK) family that plays a role in modulating hypertension and cardiologic disorders." (PMID 37239846, 2023). "ULK4 and FHIT genes have 17 and 10 EH-associated SNPs, respectively, while FNDC3B, FHIT, NPPC-DIS3L2, GLI2, and RBM47 include SNPs that have a ≥4 log-p value association with hypertension in the studied cohort." (PMID 35629146, 2022).
schizophrenia (10 papers, 2016 to 2024). A major psychotic disorder characterized by abnormalities in the perception or expression of reality. "ULK4 has been proposed to be a rare susceptibility gene for psychiatric disorders, especially schizophrenia." (PMID 38326862, 2024). "Recent studies have implicated Ulk4 as a risk factor for neuropsychiatric disorders, including schizophrenia." (PMID 38096226, 2023). "Another study implicated that SNPs rs7651623 and rs2030431 of ULK4 are associated with the risk of discontinuing the use of antipsychotics in patients with schizophrenia." (PMID 35493088, 2022). "The big splice variant of ULK4’s deletions that remove exons 33 and 34 were also more prevalent in schizophrenia patients." (PMID 36313375, 2022). "Here, we demonstrated that Unc-51-like kinase 4 (Ulk4), a novel risk factor for major mental disorders including schizophrenia, is involved in the corticogenesis." (PMID 34235142, 2021). "We conclude that Ulk4 plays an essential role in normal brain development and when defective, the risk of neurodevelopmental disorders such as schizophrenia is increased." (PMID 27670918, 2016). "We have identified recently through genetic and in vitro functional studies, a novel serine/threonine kinase gene, unc-51-like kinase 4 (ULK4), as a rare risk factor for major mental disorders including schizophrenia." (PMID 27670918, 2016). "Through a meta-analysis of several large cohorts worldwide, we reported recently a serine/threonine kinase gene, unc-51-like kinase 4 (ULK4), as a novel, rare risk factor for human schizophrenia, autism and major depression." (PMID 27670918, 2016). "Recently, emerging evidence has suggested that ULK4 may be etiologically involved in a spectrum of neuropsychiatric disorders including schizophrenia, but the underlying mechanism remains unaddressed." (PMID 35493088, 2022). "All these studies strongly suggest that ULK4 may be a rare risk factor for neuropsychiatric disorders including schizophrenia but more evidence is warranted in the future." (PMID 35493088, 2022). "Since we first reported that ULK4 may be a rare susceptibility gene for schizophrenia in 2014, research on this gene has been springing up in the neuropsychiatric field." (PMID 35493088, 2022). "This interactome closely regulates the expression of p-Akt and p-GSK-3α/β, and mice with ULK4-targeted deletion in the excitatory neurons of the forebrain present a spectrum of core features of schizophrenia." (PMID 35493088, 2022). "In our previous research using the cohort data from the International Schizophrenia Consortium, we identified four schizophrenia patients with ULK4 intragenic fragment deletions spanning from exon 21 to exon 34 among 3,391 schizophrenia patients." (PMID 35493088, 2022). "In the Decode database, ULK4 deletion was also enriched in patients with schizophrenia (2/708), bipolar disorder (2/1,136), and autism (1/507)." (PMID 35493088, 2022). "After analyzing two big databases (International Schizophrenia Consortium and Decode), we have reported that recurrent deletion of Ulk4 co-segregates a spectrum of neurodevelopmental disorders including autism and SCZ." (PMID 34235142, 2021). "Based on the supportive datasets from the International Schizophrenia Consortium and Decode, we recently have identified Unc-51-like kinase 4 (Ulk4) deletion as a rare copy number variation for a range of mental illnesses including schizophrenia." (PMID 34235142, 2021). "Using a lentivirus-mediated gene knockdown approach, we have demonstrated that depletion of ULK4 in human neuroblastoma cells (SH5Y-SY) alters multiple signalling pathways (MAPK, p38, PKC, and JNK) associated closely with stress and schizophrenia." (PMID 27670918, 2016). "Ulk4 disruption leads to multiple abnormalities common to multiple neurodevelopmental disorders, including schizophrenia and autism." (PMID 27670918, 2016).
schizophrenia (continued). "In 2014, we first reported that Unc-51-like kinase 4 (ULK4) is crucial for neuritogenesis and neuronal motility and, when defective, may predispose people to neuropsychiatric disorders including schizophrenia." (PMID 35493088, 2022). "Neuroanatomic analysis demonstrated normal brain morphology in Ulk4+/tm1a mice, with no schizophrenia-related or hydrocephalus-related phenotype." (PMID 29391390, 2018). "Interestingly, CTNNB1, an essential component in the WNT signalling pathway and a 3′-flanking gene of ULK4, participates in hippocampal network regulation and contributes to the decreased GAD67 expression in both schizophrenia and bipolar patients." (PMID 27670918, 2016). "The current study characterized behavior of heterozygous Ulk4+/tm1a mice, demonstrating that Ulk4+/tm1a mice displayed no schizophrenia-like behavior in acoustic startle reactivity and prepulse inhibition tests or depressive-like behavior in the Porsolt swim or tail suspension tests." (PMID 29391390, 2018). "We demonstrated that the Ulk4+/tm1a mice exhibited anxiety-related phenotype, with no significant alteration in schizophrenia-related behavior such as prepulse inhibition (PPI), acoustic startle reactivity (ASR), or depression-like behavior of Porsolt swim test (PST) and tail suspension test (TST)." (PMID 29391390, 2018).
ciliopathies (5 papers, 2016 to 2024). "Altogether, these studies demonstrate that ULK4 plays a vital role in ciliogenesis and that deficiency of ULK4 causes hydrocephalus and other ciliopathy-related phenotypes prevalent in neurodevelopmental and neuropsychiatric disorders." (PMID 38523660, 2024). "It should be noted that Ulk4 was recently proposed as a ciliopathy-relevant gene, as Ulk4 deletion unanimously causes severe congenital hydrocephalus in mice, which is often associated with a disarranged axoneme assembly and disrupted function of motile cilia." (PMID 34235142, 2021). "We assume that Ulk4-relevant diseases may be linked with ciliopathies, neurodevelopmental disorders and psychosis." (PMID 27670918, 2016). "The results demonstrate that ULK4 is crucial for ciliogenesis and ciliopathies." (PMID 35493088, 2022). "However, the relationship between Ulk4 and ciliopathy is an attractive research field, and further follow-up studies need to be warranted." (PMID 34235142, 2021). "It is also thought that ULK4 may contribute to ciliopathies." (PMID 39765701, 2024). "Thus, it is highly likely that ULK4 contributes to ciliopathies." (PMID 35493088, 2022).
multiple myeloma (5 papers, 2017 to 2025). "Likewise, much remains to be learned about the role of PSORS1C2 (psoriasis susceptibility 1 candidate 2) at 6p21.3 and ULK4 (unc-51 like kinase 4) in the natural history of myeloma." (PMID 31139207, 2019). "Although previous GWAS studies have suggested that ULK4 is a risk locus for multiple myeloma and interindividual diastolic blood pressure variation, emerging evidence also supports the idea that ULK4 genetic variants may cosegregate people with multiple neuropsychiatric disorders." (PMID 35493088, 2022).
acute aortic dissection (4 papers, 2019 to 2025). "Other genes associated with aortic area in our analyses have previously been associated with risks of acute aortic dissection (ULK4, LRP156)." (PMID 35922433, 2022). "In the previous GWAS of acute aortic dissection, rs2272007 was shown as a nonsynonymous SNP in the exonic region of ULK4 (PMTAG = 6.58 × 10−6)." (PMID 41251448, 2025).
Anxiety (4 papers, 2016 to 2023). Intense feelings of nervousness, tension, or panic often arise in response to interpersonal stresses. "Thus, the data suggest that Ulk4 deletion modulates brain development and results in GABAergic changes which may underlie the anxiety-related phenotype." (PMID 29391390, 2018). "In this study, we report the first evidence that Ulk4 regulates GABAergic signaling in the brain, and Ulk4 heterozygous mice display anxiety-related phenotype, a prominent component of many neuropsychiatric diseases." (PMID 29391390, 2018). "In summary, we have shown for the first time that Ulk4 haploinsufficiency in mice leads to increased anxiety-related behavior with disturbed GABAergic signaling." (PMID 29391390, 2018). "Despite the subtle differences in responses between males and females in individual tests, taken together, the behavioral data demonstrate an anxiety-like phenotype in Ulk4+/tm1a mice." (PMID 29391390, 2018). "This further confirmed anxiety-like or neophobia-like behavior in Ulk4+/tm1a mice." (PMID 29391390, 2018). "Thus, both male and female Ulk4 mutants exhibit anxiety-related behavior in several behavioral paradigms, although some sex-related differences were noted." (PMID 29391390, 2018). "However, Ulk4+/tm1a mice display anxiety-related behavior in a number of behavioral paradigms." (PMID 29391390, 2018). "However, Ulk4+/tm1a mice exhibited an anxiety-like behavioral phenotype in several tests." (PMID 29391390, 2018). "Thus, Ulk4+/tm1a mice display an elevated anxiety-like behavior in the EPM." (PMID 29391390, 2018). "Both Ulk4+/tm1a male and female mice spent significantly less time on the open arms but more time in the closed arms in the EPM test, a well-recognized measure of anxiety-related behavior." (PMID 29391390, 2018).
Hydrocephalus (4 papers, 2016 to 2024). Hydrocephalus is an active distension of the ventricular system of the brain resulting from inadequate passage of CSF from its point of production within the cerebral ventricles to its point of absorption into the systemic circulation. "Ulk4 malfunction also affects motile ciliogenesis of ependymal cells in mutant mice, leading to hydrocephalus." (PMID 38096226, 2023). "Although Ulk4−/− mutant mice are available, the majority of them presents with severe congenital hydrocephalus due to disrupted motile cilia protruding from ependymal cells, which frequently associates with brain hemorrhage accompanied by fibrosis, neuroinflammation and neovascularization." (PMID 27670918, 2016). "Therefore, caution is needed to interpret the phenotypes emanating from Ulk4−/− mice because they may result from the hydrocephalus and not from the direct consequences of Ulk4 deletion." (PMID 27670918, 2016).
autism (3 papers, 2016 to 2021). Persistent deficits in social interaction and communication and interaction as well as a markedly restricted repertoire of activity and interest as well as repetitive patterns of behavior. "On the other hand, we have observed ULK4 deletion in Caucasian autism populations." (PMID 27670918, 2016).
mental disorder (3 papers, 2016 to 2022). A disease that has its basis in the disruption of mental process. "Detailed molecular pathways are yet to be established, but Ulk4 hypomorph mice displayed dysregulated inhibitory circuits and reduced white matter integrity, the two most frequent phenotypes that predispose mental disorders and neurodevelopmental diseases." (PMID 34235142, 2021).
Stroke (3 papers, 2019 to 2022). Sudden impairment of blood flow to a part of the brain due to occlusion or rupture of an artery to the brain. "Genetic variants of ULK4, CAV2, HTRA1 and KLF12 are all associated with increased risk of stroke and the orthologous genes were upregulated in brain art ECs in obesity." (PMID 36400935, 2022). "These loci provide insights into lacunar stroke pathogenesis, highlighting disruption of the vascular extracellular matrix (COL4A2, LOX, SH3PXD2A, GPR126, HTRA1), pericyte differentiation (FOXF2, GPR126), TGF-β signalling (HTRA1), and myelination (ULK4, GPR126) in disease risk." (PMID 33773637, 2021). "In their paper, they also mentioned that ULK4 may contribute stroke." (PMID 32038707, 2019).
bipolar disorder (2 papers, 2021 to 2022). A disorder of the brain that causes unusual shifts in mood, energy, activity levels and the ability to carry out day-to-day tasks. "Similarly, SNP rs17210774 of ULK4 is significantly associated with bipolar disorder in Caucasians and another SNP rs1722850, which is close to but downstream of ULK4, is related to major depressive disorders." (PMID 35493088, 2022).
congenital hydrocephalus (2 papers, 2021 to 2022). Hydrocephalus that is present at birth. "In addition, both ULK4 knockout and hypomorphic mice presented congenital hydrocephalus featuring dilated ventricles and CSF accumulation." (PMID 35493088, 2022). "Both ULK4 null knockout and hypomorphic mice present disturbed motile cilia development and disorganized ciliary beating which impair CSF flow and eventually lead to congenital hydrocephalus." (PMID 35493088, 2022).
endometrial carcinoma (2 papers, 2019 to 2021). A malignant tumor arising from the epithelium that lines the cavity of the uterine body. "ATG7 and ULK4, which are core autophagy genes, showed effective selection of mutations in renal cancer and endometrial cancer, respectively, indicating that the expression and mutation of ULK4 may be closely related to autophagy." (PMID 33937013, 2021). "Remarkably, endometrial carcinomas showed a high number of mutations in ATG4C, RB1CC1/FIP200, and ULK4 genes." (PMID 31850214, 2019). "Authors found somatic mutations in a number if autophagy genes including RB1CC1/FIP200, WDR45/WIPI4, ULK4, and ATG7 in endometrial carcinoma and clear cell renal carcinoma." (PMID 31850214, 2019).
language delay (2 papers, 2018 to 2021). "A recent study of the Brain and Body Genetic Resource Exchange (BBGRE) cohort also reported a morbidity of 1.2‰ population, displaying ULK4 copy number variations and exhibiting pleiotropic neurodevelopment problems including learning difficulty and language delay." (PMID 34235142, 2021).